POSTN (periostin)
Diseases named in the same sentence as POSTN in open-access papers (continued):
Sharing a sentence is not in itself a finding about the gene and the disease.
asthma (continued). "Periostin (cut-off ≥50 ng/ml) was investigated as a predictive biomarker for therapeutic effect (measured as reductions in the exacerbation rate) in Phase III trials of the anti–IL-13 mAb lebrikizumab for the treatment of uncontrolled asthma, but proved inconsistent." (PMID 31315668, 2019). "However, limited data suggest that the serum periostin level predicts asthma exacerbations." (PMID 31443563, 2019). "The development of point-of-care testing and non-invasive devices (one validated recently for the blood eosinophil count, others in study for the assessment of serum IgE and periostin) could accelerate the path leading to a precision medicine approach and clinical management of severe asthma." (PMID 30598830, 2018). "Moreover, not only serum periostin but also serum TNC might have potential use as novel biomarkers for asthma." (PMID 30473714, 2018). "We sought to explore the plasma levels of biomarkers associated with asthma (periostin, TSLP and YKL-40), COPD (NGAL) and their possible correlation with lung function, the bronchodilator response and radiographic imaging in patients with asthma, COPD and with features of ACO." (PMID 29580282, 2018). "However, this study suggested that serum TNC levels may reflect disease severity in asthma and may be an indicator of airflow limitation in asthmatic patients with high serum periostin levels or high serum total IgE levels." (PMID 30473714, 2018). "In addition, asthma therapy with new biologicals, for example anti–IL-5 or anti–IL-13, appears to be far more effective if patients are selected using cellular (eg, eosinophils) or molecular (eg, periostin) biomarkers." (PMID 26334389, 2016). "The novelty of the current study is that high serum periostin concentrations appears to predict acute asthma exacerbations in the following year, providing evidence for the potential association between persistent TH2- or IL-13–driven inflammation and greater risk for loss of asthma control." (PMID 27965769, 2016). "Although lymphocyte cultures might not be practical as routine clinical biomarkers, further research might be anticipated to reveal more practical novel biomarkers of IFN-γhigh and IL-17Ahigh SR asthma similarly to the development of periostin as a biomarker of TH2high asthma." (PMID 25772594, 2015). "It is hypothesized that periostin plays an important role in eosinophilic forms of asthma." (PMID 25981515, 2015). "Next, we analysed expression of the periostin (POSTN) gene, a known signature in BECs for T2‐high asthma." (PMID 41099307, 2026). "Emerging candidates like periostin, YKL-40, and IL-17 have shown promise, but they are either costly, less accessible, or limited to specific asthma endotypes." (PMID 40546825, 2025). "IL‐4 and IL‐13, together with TGF‐β, stimulate the production of periostin, which then promotes fibroblast differentiation and EMT in asthma." (PMID 40777200, 2025). "We further used a one-to-one format for comparison and validated with the GSE63142 dataset The genes CEACAM5, PRR4, CPA3, POSTN, TCN1, CST1 (Cystatin-SN), CLCA1, TPSAB1 and NOS2 (Nitric oxide synthase 2) were highly expressed in patients with asthma." (PMID 39963184, 2025). "Although various studies have examined the association between different biomarkers and AHR, few have simultaneously measured both periostin and YKL-40 to investigate their relationship with AHR in children with asthma." (PMID 39534447, 2024). "The expression of hub genes, including CCDC167, POSTN, SEC14L1, and SERPINB2, was significantly lower in healthy donors (controls) compared to asthma patients." (PMID 38580753, 2024). "This study aimed to investigate the relationship between serum periostin levels and airway hyperresponsiveness (AHR) and between serum YKL-40 levels and AHR in children with asthma, comparing periostin as a marker for Th2 inflammation and atopy with YKL-40." (PMID 39534447, 2024).
asthma (continued). "Venn diagram analysis results demonstrated that CST1, POSTN, CPA3, and SERPINB2 were not only candidate genes in key modules but also DEGs in AR and asthma." (PMID 36733482, 2023). "In a cohort study of 40 patients with mild-to-moderate asthma, serum periostin decreased from 90 to 59 ng/mL during 4 weeks of ICS treatment, which correlated with an increase in peak expiratory flow rate (68 L/min) and in Asthma QOL." (PMID 40980110, 2023). "Serum periostin levels respond partially to ICS therapy, possibly reflecting a reduction in airway inflammation and wall thickening in asthma." (PMID 37108417, 2023). "The asthma patients were classified into T2-high asthma (n = 22), and T2-low asthma (n = 20) according to the relative expressions of type 2 signature genes, SERPINB2, CLCA1 and POSTN." (PMID 37152983, 2023). "Analysis of the enriched genes derived from the pathway analysis identified seven genes expressed in both the asthma and lung cancer sets: BCL3, POSTN, PPARD, STAT1, MYC, CD44, and FOSB." (PMID 35406434, 2022). "Further comparison of the expression of marker genes in all cell subtypes in control and asthma revealed marker genes like DCN, COLOA1, COX4L2, CLEC3B, EPAS1 and POSTN belonging to stromal cells remained the most variable genes." (PMID 36439114, 2022). "Analysis of the enriched genes derived from the pathway analysis identified seven genes present in both asthma and lung cancer: BCL3, POSTN, PPARD, STAT1, MYC, CD44, and FOSB." (PMID 35406434, 2022). "Other studies showed that the gene and/or protein expression of collagen I, fibronectin, versican, elastin, tenascin C, periostin, and vimentin was increased in ASMC and PF in asthma studies, including in vivo, ex vivo, in vitro, and animal model studies." (PMID 35456903, 2022). "Approximately half of the asthma subjects (n = 22) with consistently high expression of a signature of Type 2 inflammation (SERPINB2, POSTN and CLCA1) were identified as Th2-high asthma, and 20 asthma subjects were identified as Th2-low asthma." (PMID 35550122, 2022). "In dataset GSE4302, subjects with asthma were divided into Th2-high and Th2-low groups according to the expression of the SERPINB2, POSTN and CLCA1 genes." (PMID 35550122, 2022). "Seventy subjects (28 healthy control subjects and 42 asthma subjects) in datasets GSE4302 underwent unsupervised hierarchical clustering based on the microarray expression levels of SERPINB2, POSTN and CLCA1." (PMID 35550122, 2022). "Candidate DEGs including SERPINB2, POSTN, and CLCA1 have already been reported to participate in asthma." (PMID 35126350, 2021). "As demonstrated by others, quantification of expression of the LAE asthma-related genes CLCA1, SERPINB2 and POSTN confirmed they were up-regulated in asthmatics vs controls." (PMID 34233672, 2021). "The type 2 status of asthma was defined by the expression of the type 2 signature genes (CLCA1, POSTN, and SERPINB10) in the epithelial brushings as previously reported." (PMID 33945508, 2021). "Very strong correlations between local periostin, TSLP, eosinophils, and IL-4 in asthma point to the link between periostin–TSLP and Th2 response." (PMID 33203095, 2020). "Thus, the periostin–TSLP axis may be a potential future therapeutic target in asthma." (PMID 33203095, 2020). "A strong positive correlation between IS periostin and TSLP protein levels (r = 0.95, p < 0.001) as well as mRNA expression level (r = 0.95, p < 0.001) was found in patients with asthma." (PMID 33203095, 2020). "For examples, significant DEGs in our list are involved biomarkers of Th2 response (POSTN), inflammation (NOS2, ALOX15) and mucus production (MUC5AC) corroborated with a previous metanalysis of airway gene expression in asthma." (PMID 32900903, 2020). "A strong positive correlation between IS periostin and TSLP protein levels (r = 0.96) as well as mRNA expression level (r = 0.95) was found in patients with asthma." (PMID 33203095, 2020).
asthma (continued). "Upgraded levels of periostin and TSLP in serum, induced sputum (IS), and bronchoalveolar lavage fluid (BALf) have been reported in patients with asthma and chronic obstructive pulmonary disease (COPD)." (PMID 33203095, 2020). "Significant differences in sputum periostin and TSLP mRNA expressions were shown, with the highest values in asthma and the lowest in controls." (PMID 33203095, 2020). "Most patients with concomitantly elevated levels of sputum eosinophils, periostin, and TSLP also had also increased IL-4 and IL-13 concentrations (6/7 patients for both cytokines, which represents 50% of the asthma group)." (PMID 33203095, 2020). "However, it is unclear in our study whether periostin is associated only with EIB or with asthma control because we did not have a group of patients exhibiting frequent exacerbations of asthmatic symptoms." (PMID 30937129, 2019). "We investigated the relationship between serum levels of periostin and EIB in pediatric asthma patients." (PMID 30937129, 2019). "Among them, periostin and TSLP are well-characterized T-helper 2 type markers with specific roles in various stages of asthma pathogenesis." (PMID 29580282, 2018). "The use of periostin in distinguishing EGPA from other eosinophilic syndromes, including isolated asthma, deserves further exploration." (PMID 30308057, 2018). "Periostin levels in EGPA were significantly higher than previously studied healthy controls and patients with asthma." (PMID 30308057, 2018). "Periostin levels in EGPA are higher than in other previously studied cohorts, including healthy populations and patients with asthma, and are relatively stable over time." (PMID 30308057, 2018). "In this study, ITLN-1 mRNA significantly correlated with FeNO and serum IgE, as well as iNOS, CCL26, periostin and DPP4 mRNA in SN-Asthma, as these genes are known to be induced in BECs stimulated with IL-13." (PMID 28775743, 2017). "Given that measuring monomeric periostin is useful in treating IPF, we compared the ratios of monomeric periostin in IPF and three other high-periostin diseases: AD, SSc, and asthma." (PMID 28355256, 2017). "The IL-13 response signature (CLCA1, POSTN, SERPINB2) was also upregulated in the central airways in severe asthma compared to health, however, to a lesser extent compared to peripheral airways, and it did not attain significance." (PMID 28045928, 2017). "Heterogeneity in the severe asthma samples was evaluated using the IL-13 disease signature (CLCA1, SERPINB2 and POSTN) and the gene expression marker for steroid response (FKBP5)." (PMID 28045928, 2017). "In the SN-Asthma group, ITLN-1 mRNA correlated with FeNO, IgE, iNOS, CCL26, periostin and DPP4 mRNA, all Type-2 related parameters." (PMID 28775743, 2017). "Furthermore, additional carefully designed studies are needed to evaluate if periostin, alone or in combination with other more conventional biomarkers, can be utilized in better redefining current asthma phenotypes and selecting patients for emerging asthma therapeutics targeting Th2 inflammation." (PMID 26430389, 2015). "In a Phase II clinical study of subjects with uncontrolled asthma, despite inhaled corticosteroids (ICS), it was demonstrated that periostin status predicted the response to an anti-IL-13 monoclonal antibody, lebrikizumab." (PMID 24146092, 2014). "Epidemiological studies in patients with and without asthma have reported significantly higher periostin concentrations in non-asthmatic Chinese individuals when compared to non-asthmatic Caucasian participants." (PMID 40053143, 2025). "Besides, post-hoc analyses suggested potential benefits in subgroups, such as patients with FEV1 reversibility ≥12% and elevated biomarkers (DPP-4, periostin), showing improvements in exacerbation rates, FEV1, and asthma control." (PMID 40564060, 2025). "Anyway, because of high variable levels and lack of standardization, periostin is not currently believed to be a valuable biomarker of severe asthma." (PMID 40649123, 2025).
asthma (continued). "For example, periostin and DPP-4 are being explored as potential predictors for IL-13-targeting biologics in asthma, while IL-33 and soluble IL-33R levels in sputum or serum may aid in selecting therapies that inhibit IL-33 signaling." (PMID 40004611, 2025). "Conversely, periostin failed to distinguish between moderate and severe asthma, indicating its limitation for severity classification within this population." (PMID 41374409, 2025). "Periostin is currently considered a biomarker in asthma diagnosis, although it is not a reliable severity degree indicator." (PMID 39273372, 2024). "Cases with asthma complicated by ECRS have higher serum periostin concentrations than cases with asthma without ECRS, suggesting the involvement of IL-4/IL-13 in the pathogenesis of ECRS in asthma cases." (PMID 38785953, 2024). "On the other hand, serum levels of periostin have been recognized as a biomarker of Th2-driven inflammatory responses, but its usefulness in childhood asthma has not been established." (PMID 39685659, 2024). "Finally, CCDC167, POSTN, SEC14L1, and SERPINB2 were designated as the asthma hub genes because they were characterized by all three machine learning algorithms." (PMID 38580753, 2024). "The subgroup analysis revealed that periostin levels were significantly higher in the atopic asthma group than in the healthy controls (P = 0.003), but not in the non-atopic asthma group." (PMID 39534447, 2024). "Therefore, this study aimed to investigate the relationship between serum periostin levels and AHR and between serum YKL-40 levels and AHR in children with asthma, comparing periostin as a marker for Th2 inflammation and atopy with YKL-40." (PMID 39534447, 2024). "The predictive value of the hub genes was assessed using ROC curves, and the aero under curves for CCDC167, POSTN, SEC14L1, and SERPINB2 were approximately 0.79, 0.87, 0.86, and 0.89, respectively, supporting their sensitivity and specificity in asthma diagnosis." (PMID 38580753, 2024). "The causal mediation analysis performed in that study demonstrated that there was no indirect (mediation) effect of periostin, suggesting that the effect of IgE sensitization on developing asthma was driven through pathways other than periostin." (PMID 36694181, 2023). "One disease of the airways in which periostin has been extensively studied and known to be involved in disease pathology is that of chronic rhinosinusitis (CRS), where approximately 20% of sufferers have co-morbid asthma." (PMID 36763690, 2023). "High serum periostin, TNFα, IL-4, IL-5, and the chitinase-like protein YKL-40 levels, as well as low serum IL-37 levels, were associated with exacerbated asthma in nonsmokers." (PMID 37367073, 2023). "Moreover, the expression level of CST1 was significantly positively correlated with the expression levels of POSTN, CPA3, and SERPINB2 in the bronchial epithelium of AR patients and in the nasal epithelium of asthma patients." (PMID 36733482, 2023). "Initially, very promising as an asthma biomarker, periostin failed to become a surrogate for sputum eosinophilia, but it seems to be a good biomarker for airway remodeling and can differentiate between T2 and non-T2 asthmatics/COPD." (PMID 37744693, 2023). "In addition, the volcano plot showed that CST1, POSTN, CPA3, and SERPINB2 were significantly up-regulated in the bronchial epithelium of asthma and nasal epithelium of AR." (PMID 36733482, 2023). "Periostin is pronounced to be more useful in the evaluation of response to monoclonal antibodies and systemic steroid therapy, rather than asthma diagnosis." (PMID 36326393, 2022). "Moreover, miR-221 was described to correlate with airway eosinophilia in asthma and further increased CCL-24, CCL-26, and POSTN in asthmatic airways." (PMID 36172292, 2022). "On the other hand, other studies suggest that periostin plays a protective role, rather than detrimental role in asthma." (PMID 36078171, 2022).
asthma (continued). "However, in a phase-2 RCT including 219 patients with uncontrolled asthma, lebrikizumab, an anti-IL13 mAb, significantly increased FEV1 compared with placebo, only in patients with high serum periostin levels at baseline." (PMID 36226150, 2022). "Previous studies have also indicated higher serum levels of POSTN in CRSwNP patients compared to controls, as well as higher levels of serum POSTN in patients with asthma than in those without it." (PMID 35752781, 2022). "Periostin has been suggested as a biomarker for response to lebrikizumab already from early studies on the efficacy of lebrikizumab in asthma, although it has not been validated in all subsequent studies." (PMID 36237537, 2022). "The crosstalk of periostin and TSLP is an exquisitely driving factor for asthma." (PMID 36611844, 2022). "Asthma patients with persistent airflow limitation showed higher airway and systemic biomarkers of T2 inflammation (e.g., blood and BAL eosinophilia and circulating periostin), increased blood neutrophil counts, and serum concentration of ADAM-33." (PMID 34204767, 2021). "The Elecsys® Periostin immunoassay is the only test currently under development but is being used to target periostin in asthma rather than BC." (PMID 34439139, 2021). "Given above studies, we could conclude periostin mainly secrets in some subgroups of CRS, especially in ECRS, high level of IL-5, AFRS and cormibid with asthma or allergic rhinitis." (PMID 32954441, 2021). "Salivary or sputum periostin concentrations were more sensitive than plasma/serum periostin in distinguishing between severe and non-severe asthma patients, suggesting that it is a useful marker for early diagnosis of asthma." (PMID 34439751, 2021). "POSTN functions as the downstream of IL13 and a biomarker for Th2-driven asthma, suggesting that SAE ionocytes may also be related to the pathogenesis of asthma." (PMID 32727470, 2020). "We found key asthma-associated genes including the T2-high signature genes of CLCA1, POSTN, and SERPINB2 as well as those not previously asthma-associated (e.g., CST1 and Vanin genes—VNN1–3) to be potentially influenced by aberrant H3K27ac." (PMID 33362848, 2020). "Moreover, a very strong correlation between local periostin and TSLP level suggests positive crosstalk between these two cytokines in asthma." (PMID 33203095, 2020). "In the present study, sputum periostin levels were significantly higher in CRS patients with comorbid asthma than those without asthma." (PMID 32015784, 2020). "Although serum periostin has been recognized to be related with eosinophilic inflammation in asthma, its role in COPD has not yet been elucidated." (PMID 33203095, 2020). "The results of our study show that periostin and TSLP are associated with eosinophilic airway inflammation and seem to be important drivers of asthma but not COPD pathobiology." (PMID 33203095, 2020). "The analysis of coexistence of sputum eosinophilia (>3%), high sputum periostin, and high sputum TSLP concentration (above the median value of the control group), showed that almost 64% patients with asthma had increased sputum eosinophilia with concomitant elevated levels of IS periostin and TSLP." (PMID 33203095, 2020). "There is another explanation of increased expression of periostin in lower airways even when asthma does not coexist." (PMID 32015784, 2020). "Two large phase 3 clinical trials, STRATOS 1 and STRATOS 2, explored the use of periostin and DPP-4 as biomarkers of IL-13-driven inflammatory patterns in patients aged 12–75 years with severe uncontrolled asthma treated with tralokinumab (300 mg s.c. every 2 weeks for 52 weeks) or placebo." (PMID 31866859, 2019). "Furthermore, periostin levels are higher in EGPA compared to previously-studied cohorts of healthy populations and patients with asthma." (PMID 30308057, 2018). "Periostin is significantly higher in EGPA compared to healthy populations and patients with asthma." (PMID 30308057, 2018).